IL1B (interleukin 1 beta)
Diseases named in the same sentence as IL1B in open-access papers (continued):
Sharing a sentence is not in itself a finding about the gene and the disease.
infection (continued). "IL-1β is assigned a key role in the orchestration of the complex immune response to infection and injury." (PMID 35625063, 2022). "In this experiment, the expression of hsp-70 was only significantly upregulated at 9 h post-infection, the highest expression values within the evaluated timeframe, in line with the highest tnf-α and il-1β expression levels, too." (PMID 35328519, 2022). "Here our results showed that the immune response to a mild infection simulated by low-dose LPS induced inflammatory factor IL-1b expression and decreased MMP2 expression involved in embryo implantation." (PMID 36910123, 2022). "Since we saw a change in IL-1β production both early and late during infection, we decided to examine the inflammasome." (PMID 36040164, 2022). "In comparison to fish sampled before infection, il-1β, tnf-α1, tnf-α2, mmp-9, and socs-3 expression shows a trend to reach higher levels in fish sampled on the time frame between 6 and 24 h post-infection." (PMID 35328519, 2022). "In the head-kidney, down-regulation of mpo, il1b, and mx genes was registered in all NP-exposed fish upon infection, though only that of mpo reached significance." (PMID 35163406, 2022). "In this study, we observed that upon phagocytosis of L. corymbifera, human monocytes released IL-1β during the first hours of infection, while TNF-α and IL-6 were significantly released in later stages of the infection." (PMID 36311802, 2022). "The mRNA levels of multiple pro-inflammatory cytokines, such as interleukin-1β (IL-1β), IL-6, tumor necrosis factor-α (TNF-α), and interferon-β (IFN-β), were up-regulated during the three PRV variants infection." (PMID 35458442, 2022). "WT THP-1s treated with either CASP4 or CASP5 siRNAs exhibited significantly decreased IL-1β secretion following WT Stm infection relative to WT THP-1s treated with control siRNA, in agreement with our previous observations in primary human macrophages." (PMID 35073381, 2022). "Tissue damage and infection induce the activation and release of proinflammatory cytokines, such as IL-1β, IL-2, IL-8, and TNF-α, which mediate the onset of innate immune response." (PMID 36860473, 2022). "Lenti-Spike infection significantly increased the expression of inflammatory cytokines, including IL-1β, IL-6, and TNF-α, and chemokines, including CCL-2, CCL-3, CCL-4, and CXCL-10, whereas Lipo-hACE2 decoy significantly inhibited all these effects." (PMID 35401811, 2022). "ST SPI-II has been shown to induce NLRP3 activation, and NLRP3 ablation significantly protected against ST-induced IL-1β release upon infection." (PMID 34864057, 2022). "Accordingly, an increase in cytokine transcripts (Il6, Il8, Il1a, Il1b, and Ifng) were observed in Jamaican fruit bats upon infection." (PMID 35215832, 2022). "IL-6 and IL-1β treatment also significantly reduced expression of troponin T (by nearly 50%), and this was greatly enhanced by infection with SARS-CoV-2." (PMID 34669512, 2022). "Activation of GBPs also contributes to IL-1β and IL-18 processing and secretion during infection, and induces pyroptosis through activating the NLRP3 inflammasome and promoting LPS release into the host cells cytosol." (PMID 36248872, 2022). "We found that SVA infection and 3D expression decreased IL-1β secretion after treatment with BAPTA-AM at different gradients." (PMID 35254168, 2022). "TNF-α is a primary inflammatory factor released in the skin after trauma, injury, or infection and triggers the expression of other pro-inflammatory cytokines including IL-6, IL-8, and IL-1β." (PMID 36432834, 2022). "Numerous inflammatory cells, mainly macrophages, dendritic cells, polymorphonuclear neutrophils, and inflammatory cytokines (TGF-β, TNF-α, IL-1β, IL-6, IL-10, IL-12, and IL-23), were activated in the early stages of infection." (PMID 36233337, 2022).
infection (continued). "Our results indicate that infection with WT GBS results in significantly enhanced production of IL-1β, KC, and TNF-α in the uterus, decidua, placenta, amnion, and fetus compared to uninfected controls (*P < 0.05, one-way ANOVA, #P < 0.05, Student’s t test)." (PMID 36104331, 2022). "As is well known, IL-1α is an alarmin released by dying cells, as Rickettsia infected endothelial cells are, to initiate the early phase of sterile inflammation, while IL-1β is produced by inflammasomes at sites of tissue infection or sterile injury." (PMID 36551320, 2022). "Meanwhile, the mRNA expression level of proinflammatory cytokines, IL-1β, IL-6, and TNF-α were remarkably reduced at 12–24 hpi after PR8 infection, which showed a high association with the decrease in β-TrCP." (PMID 36366524, 2022). "Our study unveils the mechanism underlying the regulation of inflammasome assembly and production of IL-1β in response to SVA infection that will help better understand the modulation of host inflammation in pathogens invasion and development of the vaccine." (PMID 35254168, 2022). "At four days post infection, spleen samples were collected for viral titring by immunological focus assay and IL-1β measurement using ELISA and immunohistochemistry staining." (PMID 35603493, 2022). "Serum CRP is a positive acute-phase protein produced by the liver following stimulation by IL-6 and IL-1β in response to infection, inflammation, or cancer." (PMID 36669027, 2022). "Our previous study has shown that P. multocida activates NLRP3 inflammasome, subsequently induces caspase-1 activation which process pro-IL-1β into biologically active IL-1β, leading to IL-1β secretion and inflammatory response against infection." (PMID 35350616, 2022). "The mRNA levels of the inflammatory factors, namely IL-1β, IL-6, and IL-8, increased gradually with the extended infection time." (PMID 36311798, 2022). "As the infection progressed from 3 dpi to 6 dpi, the ELISA result showed that levels of pro-IL-1β/IL-1β in infected tissue homogenates were increased in comparison to mock-infected (PBS) contralateral tissues (p = 0.0472)." (PMID 35215131, 2022). "In peripheral tissues, IDO1 expression takes place in dendritic cells (DCs) and macrophages, as well as microglia in the CNS, and its expression is also induced by pro-inflammatory cytokines, such as IL-6, IL-1β, IFN-γ, and TNF and by underlying infections." (PMID 35281455, 2022). "IL-1β is a pro-inflammatory cytokine that can activate macrophages and epithelial cells and respond to infection and injury." (PMID 36235644, 2022). "In bovine MDMs, infection with isolate Cb30/14 resulted in a mitigated general cellular response but a selective increase in IL-1β and IFN-γ expression." (PMID 36558755, 2022). "The primary role of TNF-α, IL-1β, and IL-6 is the regulation of inflammatory response when wounded, and during infection or immune stimulation." (PMID 35161266, 2022). "Our data showed that IL-1β mRNA transcripts were upregulated in PBMCs infected with SFTSV at various time points post infection (p.i.) or at different multiplicities of infection (MOI) as measured by RT-PCR." (PMID 35173184, 2022). "As the initiator of gouty inflammation, mature IL-1β is produced and secreted to combat infection and stimulation via recruiting monocytes/macrophages and neutrophils to the injured joints." (PMID 36248423, 2022). "Lentivirus‐mediated CD86 overexpression in macrophages showed a significant macrophage activation at early stages of infection, while NO and IL‐1β increased significantly showing stronger phagocytosis and killing ability." (PMID 36444627, 2022). "Following infection with opportunistic pathogens, cytokine expression of IL-1β, IL-6, and TNF-α in the mucosa and serum increased significantly (P < 0.05), which resulted in decreased immunity." (PMID 35769317, 2022).
infection (continued). "This response during systemic or local infection is mediated mainly by interleukin 1 beta (IL-1β), a known pyrogen released in response to activation of TLR4 and the Nlrp3 inflammasome." (PMID 34853440, 2022). "We found that the skin lesion in diabetic rats was susceptible to infection due to the wound exposure, and the levels of TNF-α, IL-1β and IL-6 in wound tissues were significantly increased on day 7 after surgery." (PMID 35130118, 2022). "In Sub AD cells, SARS-CoV-2 did not alter cytokine expression except for a modest increase in IL1B and CCL2—the latter only observed after infection with the CoV-2(P.1) variant." (PMID 36175400, 2022). "In the ex vivo organ culture (EVOC) model of ovine interdigital skin, infection with D. nodosus stimulated IL-1β release; however, CXCL8 levels increased in both infected and mock-infected explants." (PMID 36496756, 2022). "Elevated pro-inflammatory cytokine levels were detected for WNV infection at 48- and 72-h post-infection, with key inflammatory cytokines IL-1β, TNF-α, IL-6 and IL-8 showing a statistically significant increase." (PMID 36297275, 2022). "The NLRP3 inflammasome mediates activation of caspase-1 and secretion of IL-1β in response to infection and cellular damage." (PMID 35720309, 2022). "Among intraperitoneally injected fish, il-1β, tnf-α1, and tnf-α2 expression increased over time, peaking at 6 h and decreasing back to basal levels at 48 h post-infection." (PMID 35328519, 2022). "The attenuated NH/P68 presented a reduced ability to infect moM1 compared with moMφ, and moM1 released IL-1α, IL-1β, and IL-18 in response to infection with this attenuated strain." (PMID 35215216, 2022). "The high expression of pro-inflammatory cytokines IL-6, TNFα, IL-1β, and IL-8 indicates an activated M1-polarized phenotype after infection." (PMID 36619996, 2022). "TNF-α and IL-1β act through specific cell membrane-bound receptors and participate in the recruitment of polymorphonuclear neutrophils (PMNs) into the site of infection and their activation." (PMID 35614947, 2022). "Gasdermin family is well known to play a vital role in pathogen infection, while more and more studies show that both pyroptosis and its related inflammatory cytokines IL-1β and IL-18 are the key factor in the process of non-infection related diseases." (PMID 35720396, 2022). "Infection with PAO1 also significantly increased protein levels of cleaved IL-1β, demonstrating increased activation of the inflammasome pathway." (PMID 35215060, 2022). "Our data showing differences in the early innate response, particularly IL-1α and IL-1β induction by AMs, in Mtb-HT and Mtb-LT infected mice suggest that AMs in Mtb-LT infection are inept at overriding their immunoregulatory environment." (PMID 35173157, 2022). "The relative expression of type I interferon IFN-α and IFN-β mRNA transcript was increased at approximately 60- to 150-fold following infection, while IL-1β and IL-6 recorded increase fold changes of more than 20,000- and 70,000-fold, respectively." (PMID 36317079, 2022). "Upon cell infection, there is a shift from maintaining cell homeostasis and survival to an inflammatory response that is mainly composed of IL-1β." (PMID 36361818, 2022). "This indicates that the IL-1β produced by monocytes/macrophages early during infection is critical for protection from overwhelming disease." (PMID 35038917, 2022). "In bladder tissues, we detected a significant peak in the production of IL-1β only on day 4 post infection (108.38 pg/mg ± 7.84, p < 0.0001) as compared to the sham group (36.16 pg/mg ± 6.35)." (PMID 35741412, 2022). "The blood of mice was collected 12 h after infection and the inflammatory factors (including IL-1β, IL-6, and TNF-α) in serum were measured." (PMID 35493470, 2022). "At the same time, the levels of IL-1β were dramatically improved, while IL-6 lung levels seem to be unaffected by the infection." (PMID 36422642, 2022).
infection (continued). "It is also a commonly used marker of inflammation and infection along with iNOS induction and IL-1β." (PMID 36412793, 2022). "Infection with these clinical strains also led to caspase-1 activation in BMDMs and significant increases in IL-1β and IL-18 production." (PMID 35277504, 2022). "The results showed that the calves had low levels of inflammation and infection, and it was related to the anti-bacterial function of zinc, which inhibits lipopolysaccharide induced activation of NF-κB p65 and the production of IL-1β." (PMID 35847636, 2022). "First of all, the inflammasome releases the pro-inflammatory cytokine IL-1β to mediate immune cell recruitment to the site of infection." (PMID 35406754, 2022). "Given the critical role of pro-inflammatory cytokines in the macrophage response to infection, we compared the levels of TNFα and IL1β in the NT and CMPK2 knockdown (KD) macrophages in response to Mtb infection." (PMID 36451821, 2022). "Inhibition of IRE1α and PERK by inhibitors counteracted SubAB-mediated inhibition of STEC O113 ΔsubAB infection-induced IL-1β release." (PMID 35345462, 2022). "Infection induced activation of inflammatory caspases and production of pro-inflammatory IL-1β and cleaved GSDMD, leading to pyroptosis of alveolar epithelial cells and alveolar macrophages." (PMID 35271686, 2022). "HSV enters fetal circulation through infection of Hofbauer cells, placental monocytes, and induces expression of IL-1β, a pro-inflammatory cytokine." (PMID 35844234, 2022). "Upregulation of NLRP3, IL-1β, and IL-18 was also demonstrated in primary isolated human bronchial epithelial cells after a 6-h infection with PAO1." (PMID 35215060, 2022). "With the notable exception of Staphylococcus aureus, we observed that all bacteria triggered Caspase-1-dependent IL-1β release in our experimental setups, thus confirming Caspase-1 activation in neutrophils upon infection with various bacterial pathogens." (PMID 35849616, 2022). "In agreement with our in vivo infection models, R. montanensis-infected WT BMDMs produced higher levels of IL-1α and IL-1β cytokines and displayed reduced bacterial loads during the course of infection, compared to R. typhi- or R. rickettsii-infected BMDMs." (PMID 35130729, 2022). "We observed that after sixteen hours of infection monocytes produced a significant amount of IL-1β, TNF-α, IL-6 and IL-10 in response to viable fungal spores." (PMID 36311802, 2022). "Here, we focused on the change in TNF-α and IL-1β message levels in the brain tissue of mice after infection with F. nucleatum." (PMID 35813949, 2022). "First, we will discuss the data demonstrating that IL-1β is of importance for host resistance against infections with Mtb and the possible mechanisms." (PMID 35237260, 2022). "Although the overactivation of NLRP3 inflammasome and release of cytokines can cause tissue and organ damage, it is demonstrated that inflammasome and IL-1β can also provide protections in the acute phase of multiple pathogens infection." (PMID 36618363, 2022). "After infection with S. japonicum, KO rats also developed a strong pro-inflammatory response, with high production of TNF-α, IL-6, and IL-1β at all time points post-infection which reached a peak at 7 weeks post-infection." (PMID 35584107, 2022). "In support of this view, there are large increases in serum IL-1β levels in response to an acute infection 69, and consistent with their glucose sensing role, islets are highly vascularized and receive the majority of the pancreatic blood flow 70,71." (PMID 34927076, 2022). "Taken together, these results show that NLRP3 inflammasome-mediated IL-1β activation requires SVA infection, SVA genomic RNA, and protein synthesis." (PMID 35254168, 2022). "IL-1β is a potent low-abundance cytokine with activity more refined to acute injury or infection, while IFN-γ stimulates the innate and adaptive immune responses to pathogens." (PMID 35924240, 2022).
infection (continued). "We found that the mRNA expression levels of TNF-α, IL-1β and IL-6 were significantly increased after 7 days of infection, while the expression of the three inflammatory factors was decreased upon intraocular injection of LBH589." (PMID 36171756, 2022). "IL-1β was lower in the lungs of both Casp11−/− and Gsdmd−/− mice at 2 d after infection when compared to WT." (PMID 35588457, 2022). "With regard to alterations in the three inflammatory factors, both IFN-γ and IL-1β concentrations in the serum of GM chickens presented a significant increase after ST infection." (PMID 36557693, 2022). "The infection cytokines produced by interleukin (IL-6, IL-8, IL-1β), tumor necrosis factor-alpha (TNF-α), and interferon-gamma (IFN-γ) are all accompanied by a severe infection." (PMID 36421668, 2022). "Compared to the control group, chickens in the M group had increased IL-6, IFN-γ, IL-1β, and IL-10 mRNA expression on days 4, 7, and 10 post-infection (p < 0.05)." (PMID 35875532, 2022). "Meanwhile, QKI deficient RAW 264.7 cells showed increased secretion of pro-inflammatory cytokines, such as TNF-α, IL-6, IL-1β, and decreased secretion of IL-10, post-infection." (PMID 36088389, 2022). "As in WT controls, early, infection-induced mRNA accumulation of COX-2 was enhanced in IL-1α−/−/IL-1β−/− mice." (PMID 35523455, 2022). "Expression analysis of IL-1β transcripts at different infection time points showed the lowest expression during acute infection (0.0016 ± 0.0003) where the values were nearly the same as in pre infection (0.0025 ± 0.0004)." (PMID 35281029, 2022). "The pro-inflammatory cytokine IL-1β is thought to act as a mediator between the detection of infection stimuli and febrile stimuli by peripheral immune cells." (PMID 35458665, 2022). "Pathways enriched in genes upregulated in natural infection included defence response to bacteria (elim KS = 0.00022), innate immune response in mucosa (elim KS = 3.9 × 10−5) and positive regulation of IL-1B (elim KS = 0.00091)." (PMID 36271270, 2022). "In order to evaluate the influences of CRKP colonization and translocated infection on inflammatory factor expression, interleukin-1β (IL-1β), tumor necrosis factor alpha (TNF-α), IL-6, and IL-10 concentrations were analyzed." (PMID 36445086, 2022). "In contrast, the adjuvanted (VSA-1, QS-21) sCal vaccine groups showed lower levels of inflammatory cytokines (TNF-α, IL-6, IFN-γ, IL-1β) in the lung compared to the naïve mice with infection." (PMID 36146461, 2022). "The supernatants were harvested at 12 h post-infection and subjected to ELISA to determine IL-1β protein expression levels." (PMID 36503883, 2022). "The level of IL-1β was greatly increased when the cells were infected with higher multiplicity of infections of ZIKV." (PMID 36559293, 2022). "At day 4 post infection, the increase in the production of IL-1β in urethra was sustained (42.76 pg/mg ± 5.9, p = 0.036, unpaired Student’s t-test) and was significantly higher than that of sham non-infected rats (26 pg/mg ± 3.93)." (PMID 35741412, 2022). "More detailed time-course of infection studies will be needed to relate IL-10 activation/expression with changes in other cytokine levels (e.g., IL-1β and TNFα)." (PMID 35911725, 2022). "The NLRP3 inflammasome is a multiprotein complex that regulates caspase‐1 activation and subsequent interleukin (IL)‐1β and IL‐18 release from innate immune cells in response to infection or injury." (PMID 35137954, 2022). "TNF-a was equally triggered in both cases, however, the pro-inflammatory genes IL-8 and IL-1b transcribed upon TNF-a induction seem to have a higher expression following infection with the mutant isolate." (PMID 35215144, 2022). "It has been shown that leukocytes produce the majority of inflammation cytokines, including IL-1β, and these play an important role in the host’s defense against infection, necrosis, and other forms of inflammation." (PMID 36187758, 2022).